ENSG00000252249
Gene: Small nucleolar RNA gene on chromosome 6 (93,879,106 to 93,879,229, forward strand). Ensembl gene ENSG00000252249.
Homologues: Paralogues in human: SNORA18 (80% identical).